LRP1B (LDL receptor related protein 1B)
Diseases named in the same sentence as LRP1B in open-access papers (continued):
Sharing a sentence is not in itself a finding about the gene and the disease.
glioblastoma (12 papers, 2018 to 2025). The most malignant astrocytic tumor (WHO grade IV). "LRP1B’s association with poor prognosis in IDH-wildtype glioblastoma shows its emerging potential as a prognostic biomarker and a possible therapeutic target for drugs." (PMID 40564017, 2025). "On the other hand, the disclosure of potential new players associated with LRP1B presents exciting prospects for exploring them as therapeutic targets and strategies for addressing glioblastoma and other types of cancer." (PMID 37511044, 2023). "In patients with glioblastoma, LRP1B is generally down expressed, and LRP1B deletion is associated with poor outcome." (PMID 33391418, 2021). "EGFR, which encodes a receptor tyrosine kinase, is more frequently amplified in glioblastomas, whereas LRP1B, which encodes a low-density lipoprotein receptor related protein, is predominantly deleted in lung adenocarcinomas (LUAD)." (PMID 34395272, 2021). "LRP1B deletion has been strongly associated with poor prognosis in glioblastoma patients." (PMID 40564017, 2025). "In glioblastoma, approximately 4% of cases harbor mutations in LRP1B." (PMID 40564017, 2025). "LRP1B deletion is associated with poor outcome in glioblastoma patients." (PMID 38136305, 2023). "Additionally, a recent study has shown that mutations in LRP1B in glioblastoma are associated with patients' poor prognosis." (PMID 34093808, 2021). "Studies reveal that 10% of IDH1/2 wildtype glioblastoma tissues contain LRP1B deletions, significantly reducing expression in tumor samples compared to healthy tissue." (PMID 40564017, 2025). "Using a dual sgRNA CRISPR/Cas9 gene editing approach, this study aimed to assess the impact of disrupting LRP1B in glioblastoma cell biology." (PMID 37511044, 2023). "To evaluate the ability of the developed system to silence LRP1B expression in human tumor cells, we transfected the generated vectors into the U87 glioblastoma (GB) cell line (which expresses LRP1B, contrary to the great majority of tumor cell lines)." (PMID 37511044, 2023). "Genomic LRP1B losses were proposed as candidate genomic markers related to progression to glioblastoma in primary glioma cell lines." (PMID 37511044, 2023). "An increasing number of studies have shown that LRP1B is underexpressed due to homozygous gene deletions in non‐small cell lung carcinoma, glioblastoma, urothelial carcinomas, and other malignant tumors." (PMID 34152098, 2021). "LRP1B knockdown is related to worse outcomes for glioblastoma patients." (PMID 35389768, 2022).
lung adenocarcinoma (12 papers, 2017 to 2025). A carcinoma that arises from the lung and is characterized by the presence of malignant glandular epithelial cells. "Bioinformatics analysis revealed significant differences in the expression levels of PD‐L1 and TMB between patients with LRP1B mutation and wild‐type patients in lung adenocarcinoma (LUAD)." (PMID 39660409, 2024). "LRP1B mutations were also described in atypical adenomatous hyperplasias, which are precursors of human lung adenocarcinomas." (PMID 35295134, 2021). "Taken together, these data suggest that the co-mutation of FAT3 and LRP1B defines a unique subset and may be a promising novel biomarker for screening candidates for ICIs therapy of lung adenocarcinoma." (PMID 35069585, 2021). "In summary, co-mutation of FAT3 and LRP1B is a promising useful biomarker for predicting the efficacy of immunotherapy, which can improve the clinical efficiency of practicing precision medicine in lung adenocarcinoma patients." (PMID 35069585, 2021). "This research provides evidence that co-mutation of FAT3 and LRP1B may be a very promising novel biomarker for screening candidates of ICIs therapy in lung adenocarcinoma and lays a preliminary foundation for subsequent further exploration." (PMID 35069585, 2021). "Moreover, LRP1B mutations were found to be overrepresented in lung adenocarcinomas in chronic obstructive pulmonary disease patients, independent of smoking status." (PMID 35295134, 2021). "In lung adenocarcinoma (LUAD), LRP1B is one of the 26 significantly mutated genes and ranks among the top five." (PMID 39660409, 2024). "Nevertheless, we believe that the data of this paper has proved that in patients with lung adenocarcinoma, the co-mutation status of FAT3 and LRP1B deserves further attention and research." (PMID 35069585, 2021). "After stepwise screening, we obtained FAT3 and LRP1B, two key genes closely related to the immunogenicity, cytotoxicity and immunotherapy response of lung adenocarcinoma patients." (PMID 35069585, 2021). "On the other hand, USH2A, LRP1B, MUC16, and SYNE1 genes have been reported to have frequently mutated in various cancer types, particularly lung adenocarcinoma and lung squamous cell carcinoma." (PMID 30555633, 2018).
breast carcinoma (11 papers, 2010 to 2024). "In external validation datasets, these associations, including deletions in PTEN and LRP1B or amplifications of MYC, CEP89 and ETV6, featured most prominently in the largest cohort of breast cancer samples." (PMID 37221612, 2023). "One study has shown that LRP1B immunoreactivity is detected in the membrane and cytoplasm of breast cancer cells from 60 of 92 patients." (PMID 38136305, 2023). "H&N cancer had the highest frequencies of LRP1B (31.6%), and breast cancer had the highest frequency of PIK3CA and MYC (32.2% and 28.7%, respectively)." (PMID 34204917, 2021). "To follow up on this analysis, we analyzed a collection of 102 sporadic breast cancers but were unable to identify internal deletions of LRP1b, suggesting that it is a relatively rare event in sporadic breast cancer, or that it is associated with a subtype of disease not represented by this dataset." (PMID 20942901, 2010). "In support of a role for LRP1b in breast tumorigenesis, it was recently shown that deletion of LRP1b is associated with the evolution of MCF10A cells, which are an immortal mammary epithelial cell line, into malignant tumors in a xenograft model of mammary cancer." (PMID 20942901, 2010). "LRP1B is a putative tumor suppressor and a member of the low-density lipoprotein receptor family; gene mutation has been reported in several cancer types but not previously in breast cancer." (PMID 30370249, 2018). "Lower mRNA expression of LRP1B and SEMA3B was detected in breast cancer than normal breast tissues, and their downregulation was in relation to poor clinical outcomes." (PMID 35186006, 2021). "The spectrum of mutations in the NZBR lines is similar to that found in commonly used breast cancer cell lines, except that the EVI2B, LRP1B and PMS2 mutations have not been reported in breast cancer lines." (PMID 30370249, 2018).
cervical carcinoma (11 papers, 2015 to 2024). A carcinoma arising from either the exocervical squamous epithelium or the endocervical glandular epithelium. "Mutation enrichment of LRP1B has been observed in HPV‐integrated cervical cancer and HPV‐positive HNSCC." (PMID 38279874, 2024). "LRP1B undergoes, in addition to mutations, deep deletions in cervical cancer for a total frequency of genetic lesions of 20%, suggesting an important tumor suppressor role." (PMID 33435133, 2021). "KMT2C and LRP1B gene mutations are independent predictors of TMB-high status in cervical cancer." (PMID 36333792, 2022). "Moreover, this study also indicated that LRP1B mutation was in a relationship with unfavorable outcomes of cervical cancer patients." (PMID 36076209, 2022). "There are limited researches that reported the mutations of LRP1B and FAT1 genes in cervical cancer previously." (PMID 36076209, 2022). "Significant differences in the personal genomic landscapes were detected across cervical cancer subtypes, and our results indicated that mutations in the KMT2C and LRP1B genes were associated with higher TMB values." (PMID 36333792, 2022). "In our study, the PIK3CA, KMT2C, KMT2D, LRP1B, and FBXW7 genes were the five genes with the highest mutation frequencies in cervical cancer samples, which is mostly consistent with the results in TCGA." (PMID 36333792, 2022). "We also showed that cervical cancers with mutations in the KMT2C and LRP1B genes have an increased TMB, and our data indicate that KMT2C and LRP1B gene mutations may serve as biomarkers to forecast therapeutic reactions." (PMID 36333792, 2022). "Some hotspot genes (e.g., KLF5, LRP1B, and KLF12) have previously been described in cervical cancer, and others (e.g., CADM2, CEP19, CSMD1, and NRROS) are reported for the first time in the present study." (PMID 34885212, 2021). "Three genes of LRP1B, FHIT, and DLG2 belong to a group of 9 genes that have been reported to be the most frequently integrated spots for HPV in cervical carcinomas." (PMID 32905102, 2020). "Three very large CFS genes FHIT, LRP1B and DLG2 were the sites of HPV integrations in multiple cervical cancers and the protein expression of FHIT and LRP1B was down regulated when HPV integrated in their introns." (PMID 26262638, 2015). "Notably, LRP1B and DLG2 are also integration hot spot genes in cervical cancer identified by long read sequencing." (PMID 38279874, 2024). "In our present study, the missense mutation of LRP1B was detected in original cervical cancer, F2-PDX models and F3-PDX models, which may potentially become a new therapeutic target for cervical cancer patients, and further study will be needed to discover a novel and efficient targeted therapy." (PMID 36076209, 2022). "Although several studies have investigated the relationship between LRP1B and TMB, no studies have provided definitive findings for cervical cancer." (PMID 36333792, 2022).
colorectal cancer (11 papers, 2017 to 2025). A primary or metastatic malignant neoplasm that affects the colon or rectum. "Loss of LRP1B leads to changes in immune cell infiltration and can be used as a therapeutic target for colorectal cancer." (PMID 39532036, 2024). "In this study, the mutation frequency of LRP1B in colorectal cancer was 17 %." (PMID 39532036, 2024). "LRP1B mutation (T-low: 17.4%, T-high: 34.1%; p = 0.038) was also more frequent at T3 and T4 stages, and this gene has been reported to inhibit the progression of colorectal cancer cells." (PMID 35003350, 2021). "LRP1B may serve as a potential colorectal cancer therapeutic target, and its absence leads to changes in immune cell infiltration." (PMID 39532036, 2024). "Firstly, we extracted mRNA from different colorectal cancer cell lines (RKO, HCT15, SW480, SW620, LS180, DLD-1, and HCT116) and tested the expression of LRP1B." (PMID 40170839, 2025). "SEISMIC also reported several large cancer genes not detected in the other studies, including CSMD3 (3,707 amino acids) in UCEC and STAD, and LRP1B (4599 amino acids) in STAD and colorectal cancer (CRC)." (PMID 36396655, 2022).
ovarian carcinoma (11 papers, 2020 to 2025). A malignant neoplasm originating from the surface ovarian epithelium. "Recurrently mutated ovarian cancer driver genes, including LRP1B, KMT2A, ARID1A, KMT2C and ATRX were also found in two cell lines." (PMID 37525498, 2023). "As a tumor suppressor, LRP1B mutation was associated with favorable outcomes to immune checkpoint inhibitor across multiple cancer types, and LRP1B protein was a predictor of response to pegylated liposomal doxorubicin in patients with ovary cancer." (PMID 36721777, 2023). "In this study, we detected a high frequency of LRP1B mutations in older ovarian cancer patients." (PMID 33432021, 2021). "LRP1B disruption has been shown as a potential contributor to the emergence of chemotherapy resistance in ovarian cancer." (PMID 38566223, 2024). "CCDC80, also known as LRP1B (Low-Density Lipoprotein Receptor-Related Protein 1B), is gaining recognition as a candidate gene in ovarian cancer prognosis." (PMID 37958970, 2023). "A recent study also identified LRP1B, which encodes low-density lipoprotein receptor-related protein 1B, as a novel tumor suppressor, and LRP1B deletion was associated with chemotherapy resistance in ovarian cancer." (PMID 34980012, 2022). "More recently, the expression of LRP1B was evaluated for the first time at protein level in a series of ovarian cancer patients." (PMID 34577535, 2021). "Functional studies in ovarian cancer cell lines showed that LRP1B overexpression (with a mini-receptor) increased their sensitivity to liposomal doxorubicin, while its downregulation had the opposite effect." (PMID 34577535, 2021). "However, liposomal Doxorubicin was found to be ineffective in ovarian cancer with LRP1B (p.S1148P and p.W3333L)." (PMID 38672648, 2024). "Similarly, LRP1B is often inactivated in CLL or ovarian cancer, while we find it inactivated by deletion in one of the lung tumors." (PMID 33670576, 2021). "Together, we deduced that MED12, LRP2, PIK3R2, CCNE1, and LRP1B might be potential biomarkers for immunotherapy of ovarian cancer." (PMID 33432021, 2021). "We also observed a common deleted region on 2q22.1 that included the gene LRP1B in the NSCLC cell lines and an additional common region only shared by the ovarian cancer cell lines on 9q22.33 that included part of the gene TMOD." (PMID 32224864, 2020).
prostate carcinoma (9 papers, 2019 to 2024). A carcinoma that arises from epithelial cells of the prostate gland. "Patients with heavily pretreated castrate-resistant prostate carcinoma carrying LRP1B mutations had significantly better (75%) and longer response to anti-PD-1 antibody pembrolizumab than non-carriers (14%)." (PMID 33255265, 2020). "Hypoxia-induced miR-301b-3p expression promotes prostate cancer progression through targeting LRP1B." (PMID 39525474, 2024). "Study showed that hypoxia upregulates miR-301b-3p to promote the occurrence, metastasis and progression of prostate cancer by targeting LRP1B." (PMID 39525474, 2024). "miR-500 could promote cell growth via targeting LRP1B in prostate cancer." (PMID 34676206, 2021).
pancreatic cancer (8 papers, 2014 to 2023). "LRP1B (low-density lipoprotein receptor-related protein 1B) gene mutations were frequently seen in multiple types of human cancer and had been recognized as driver mutations in liver cancer and pancreatic cancer." (PMID 34720757, 2021). "Two SNPs in atopy-related immunologic candidate genes LRP1B were associated with pancreatic cancer risk, even after adjustment for multiple comparisons." (PMID 31164891, 2019). "It is also possible that the biologic mechanism responsible for the association we observed between LRP1B and pancreas cancer risk is unrelated to the immune system." (PMID 25945796, 2015). "Several observations favor LRP1B being a bona fide driver mutation in many tumors, including a very high frequency of homozygous deletions, and frequent point mutation in esophagus, oral, liver, colon, gastric, breast, thyroid, and pancreatic cancer." (PMID 31164891, 2019). "Although most of these LRP1B functions have been defined in different studies, it is interesting to see that inflammation, a core process of asthma and cancer, is now also genetically associated with both asthma and pancreatic cancer (this study) at the LRP1B locus." (PMID 25945796, 2015).
cognitive decline (6 papers, 2010 to 2023). "MYT1L gene, LRP1B gene and NEDD4L gene show strong associations with AD, and leading to cognitive decline in AD." (PMID 37510227, 2023). "Previous research has shown that haplotypes in the LRP1B gene can protect the aged from cognitive decline." (PMID 31649738, 2019). "Two genetic variants were identified (PMeta < 2.59 × 10−8) to be associated with healthy aging, including the LRP1B locus previously associated in long-lived individuals without cognitive decline." (PMID 35927272, 2022). "Germline SNPs/ haplotype in LRP1B have been associated with aging without cognitive decline; however, associations of germline SNPs with incidence/progression of cancer and pharmacogenomics have yet to be reported." (PMID 27047539, 2016). "A study of genome screen have identifies that LRP1B is significant and protective for successful aging without cognitive decline." (PMID 26621834, 2015). "In our list of 1372 gene probe signature we also have another member of this family, LRP1B (low density lipoprotein-related protein 1B (deleted in tumors)), While LRP10 appears to be positively upregulated with cognitive decline an inverse relationship is observed for LRP1B." (PMID 20405009, 2010). "Besides, gene LRP1B is significant for successful aging without cognitive decline." (PMID 26621834, 2015).
liver cancer (6 papers, 2021 to 2022). An epithelial or non-epithelial malignant neoplasm that arises from the liver. "A research by Ikari and colleagues suggested that LRP1B was one of most prominant somatic mutations in liver cancer metastasis, which initiated the key LRP1B function in HCC." (PMID 34386813, 2021). "Interestingly, LRP1B have been described as a common target gene for HBV integration in liver cancer." (PMID 36243813, 2022).